ADAMTS16 (ADAM metallopeptidase with thrombospondin type 1 motif 16)
Diseases named in the same sentence as ADAMTS16 in open-access papers (continued):
Sharing a sentence is not in itself a finding about the gene and the disease.
tumor (10 papers, 2017 to 2025). "Expression of both PXDN (which encodes peroxidasin) and ADAMTS16 were significantly up-regulated in adenocarcinoma tumours compared to matched adjacent normal lung tissue (1.96-fold and 10.7-fold change in median expression, respectively)." (PMID 37397358, 2023). "The other selected extracellular tumour marker candidate, ADAMTS16, a matrisome-associated protease, targets fibronectin to inhibit ECM assembly, further suggesting that ECM organisation is dysregulated in NSCLC tissue." (PMID 37397358, 2023). "In summary, this study indicates that ADAMTS16 plays a role as a tumor promoter and its upregulation is associated with a poor prognosis in GC." (PMID 36232317, 2022). "Our results showed that exogenously expressed ADAMTS16 missense mutations inhibited cell growth or sensitized tumor cells to cisplatin and inhibited tumor growth in vivo." (PMID 29179445, 2017). "The oxidation and reduction in disulfide bonds in ADAMTS16 enzyme and associated receptors may act as a key regulatory switch for tumor-promoting activity and drug resistance in cancer cells." (PMID 41440381, 2025). "IHC staining of tumor tissues further confirmed the inhibition of ADAMTS16 in the ADAMTS16-knockdown group." (PMID 39551781, 2024). "Previous studies have shown that ADAMTS16 expression inhibits the proliferation of tumor cells, whereas our data suggested that circADAMTS16 promotes adipocyte proliferation." (PMID 37190084, 2023). "A disintegrin and metalloproteinase with thrombospondin motifs 16 (ADAMTS16), another protease, was up-regulated in tumour samples (2.0-fold)." (PMID 37397358, 2023). "Of the extracellular proteins we quantified as up-regulated in tumours, we selected peroxidasin and ADAMTS16 for further analysis." (PMID 37397358, 2023). "In tumours, peroxidasin and ADAMTS16 were found variably distributed between tumour stroma and tumour cells." (PMID 37397358, 2023). "The DNA of ADAMTS16 displays a hypermethylation state in colorectal tissue and can inhibit tumor proliferation." (PMID 32884571, 2020). "IHC analyses determined that both peroxidasin and ADAMTS16 were enriched in tumour cell-rich regions of lung tumour tissue, although IHC scoring of either of these candidates did not represent a significant predictor of survival in the TMA cohort of NSCLC patients." (PMID 37397358, 2023). "Ectopic ADAMTS16 expression significantly promoted tumor cell migration, invasion, and growth." (PMID 36232317, 2022). "Ki67 and TUNEL showed that ADAMTS16 promoted tumor cell proliferation." (PMID 36232317, 2022). "Accordingly, ADAMTS16 may function as a pro-tumor factor in GC development and progression in vivo, such that ADAMTS16 stimulated tumor growth in the xenotransplantation model in this study." (PMID 36232317, 2022). "However, ADAMTS16 was found to be highly expressed in the esophagus, and its knockout inhibited tumor invasion." (PMID 32884571, 2020). "In recent studies, ADAMTS16 may be involved in tumor biological procession." (PMID 36232317, 2022). "However, further analyses of the ADAMTS16 effects on tumor cell migration and invasion are warranted in order to find out whether ADAMTS16 might represent a novel tumor suppressor gene for CRC, LC and SCC." (PMID 30081852, 2018). "Therefore, ADAMTS16 may play a crucial role in LUAD tumor development." (PMID 39551781, 2024). "Additional hub genes MMP13, SFRP4, ADAMTS16 and FNDC1 also significantly affect survival with their expression across tumour grades comparable to CTHRC1." (PMID 36190948, 2022). "Thus, our data suggest that ADAMTS16 may act as tumor suppressor in certain epithelial cancers." (PMID 30081852, 2018). "Moreover, our results provide evidence that ADAMTS16 may have tumor suppressor properties." (PMID 30081852, 2018). "However, the exact molecular mechanisms of how these mutations sensitize tumor cells to platinum remain unclear because the original function of ADAMTS16 has not been revealed yet." (PMID 29179445, 2017).
tumor (continued). "ADAMTS16 is a crucial member of the ADAMTS family and is involved in tumor progression." (PMID 39551781, 2024). "Therefore, ADAMTS16 forms a positive feedback loop with the TGF-β1/SOX4 axis to regulate EMT and metastasis, and disruption of this feedback loop inhibits tumor progression." (PMID 39551781, 2024). "Whether ADAMTS16/NF-κB/IFI27 regulates EMT, TME, and tumor resistance still needs further study." (PMID 36232317, 2022). "According to fold changes of expression level between non-tumor and tumor, representative target genes were CLIP2, TREM1 (miR-26a), SPOCK1 (miR-375), PENK, and ADAMTS16 (miR-1260)." (PMID 32313120, 2020).
cancer (9 papers, 2017 to 2025). A tumor composed of atypical neoplastic, often pleomorphic cells that invade other tissues. "Cancer cells can invade tissues by keeping matrix-degrading enzymes like ADAMTS16 active, and for membrane receptors to continue responding to growth signals, promoting cell migration and invasion." (PMID 41440381, 2025). "We identified ADAMTS16 as novel gene with cancer-specific promoter hypermethylation in CRC, LC and SCC patients implicating ADAMTS16 as potential biomarker for these tumors." (PMID 30081852, 2018). "Gene expression analysis for the same TCGA COADREAD cohort (n = 22 (ctrl), n = 224 (canc)) revealed that ADAMTS16 mRNA expression was significantly decreased from 0.29 in the control (ctrl) to 0.04 in the cancer tissue (canc) (P < 0.0001)." (PMID 30081852, 2018). "Strikingly, 8 CpGs located in the ADAMTS16 gene were commonly differentially methylated in all three cancer entities." (PMID 30081852, 2018). "Our study in evaluating 1027 matrisome genes across cancers, has identified a novel set of genes (MMP13, FNDC1, SFRP4 and ADAMTS16) that could work with CTHRC1 to regulate cancer progression." (PMID 36190948, 2022). "Furthermore, the overall pattern of the graphs was very similar reflecting a similar ADAMTS16 methylation profile in these three cancer entities." (PMID 30081852, 2018). "Few studies have examined the role of ADAMTS16 in the pathogenesis of cancer." (PMID 29179445, 2017). "ADAMTS16 has been previously shown to drive epithelial–mesenchymal transition (EMT) and metastasis in various cancers, ultimately leading to the development of drug resistance." (PMID 41020875, 2025). "Cytohubba analysis of these genes revealed 13 hub genes, of which MMP13, POSTN, SFRP4, ADAMTS16 and FNDC1 were significantly altered in their expression with CTHRC1 and seen to affect survival across cancers." (PMID 36190948, 2022). "It would hence be of interest to look at the protein expression data in cancers for CTHRC1 and the now identified genes of interest, POSTN, MMP13, SFRP4, ADAMTS16 and FNDC1." (PMID 36190948, 2022). "Comparing malignant and non-malignant tissues of the same patients, we identified ADAMTS16 as a gene with cancer-specific promoter hypermethylation in CRC, LC and SCC patients." (PMID 30081852, 2018).
adenocarcinoma (1 paper, 2023). A common cancer characterized by the presence of malignant glandular cells. "We found that higher expression of PXDN was significantly associated with shorter survival of adenocarcinoma patients (hazard ratio (HR) = 1.57; 95% confidence interval (CI), 1.05–2.37; P = 0.028, log-rank test), whereas that of ADAMTS16 was not." (PMID 37397358, 2023).
infection (1 paper, 2013). The state of being infected such as from the introduction of a foreign agent such as serum, vaccine, antigenic substance or organism. "The genes adam and adamTS16, down-regulated in infected spat, might be involved in cellular response to infection." (PMID 23987141, 2013).
ADAMTS16 also shares sentences with these, for which no sentence is quoted: premature ovarian failure (2 papers); anorexia nervosa (1); cardiac hypertrophy (1); Cerebellar hypoplasia (1); cryptorchidism (1); ductal carcinoma in situ (1); Dupuytren’s disease (1); eczema (1); Hernia (1); hypospadias (1); invasive ductal carcinoma (1); Lewis lung carcinoma (1); microcephaly (1); Obesity (1); Urinary incontinence (1).